KCNJ2 (potassium inwardly rectifying channel subfamily J member 2)
Description:
Inward rectifier potassium channels are characterized by a greater tendency to allow potassium to flow into the cell rather than out of it. Their voltage dependence is regulated by the concentration of extracellular potassium; as external potassium is raised, the voltage range of the channel opening shifts to more positive voltages. The inward rectification is mainly due to the blockage of outward current by internal magnesium. Can be blocked by extracellular barium or cesium. Probably participates in establishing action potential waveform and excitability of neuronal and muscle tissues.
Synonyms: IRK1; Kir2.1; LQT7; ATFB9; HHBIRK1; HHIRK1; SQT3
Tractability: Small molecule: an approved drug acts on it; it belongs to a druggable protein family. Antibody: UniProt places it where antibodies can reach, with high confidence; its Gene Ontology location is reachable by antibodies, with high confidence; UniProt predicts a signal peptide or a membrane-spanning region. PROTAC: ubiquitination databases record sites on it.
Target class: Inwardly rectifying potassium channel; Potassium channels; Voltage-gated ion channel; Ion channel
Chemical probes: ML133
Gene: Protein-coding gene on chromosome 17 (70,168,302 to 70,180,044, forward strand). Ensembl gene ENSG00000123700.
Subcellular location: Cell membrane; Cell membrane, sarcolemma, T-tubule
Pathways (Reactome):
Neuronal System: Activation of G protein gated Potassium channels; Classical Kir channels; Inhibition of voltage gated Ca2+ channels via Gbeta/gamma subunits
Muscle contraction: Phase 4 - resting membrane potential
Sensory Perception: Sensory perception of sour taste
Gene Ontology:
Molecular function: identical protein binding; inward rectifier potassium channel activity; phosphatidylinositol-4,5-bisphosphate binding; protein binding; voltage-gated potassium channel activity involved in cardiac muscle cell action potential repolarization
Biological process: cardiac muscle cell action potential involved in contraction; membrane repolarization during action potential; membrane repolarization during cardiac muscle cell action potential; potassium ion import across plasma membrane; potassium ion transmembrane transport; potassium ion transport; protein homotetramerization; regulation of heart rate by cardiac conduction; regulation of membrane repolarization; regulation of skeletal muscle contraction via regulation of action potential; relaxation of cardiac muscle; relaxation of skeletal muscle; intracellular potassium ion homeostasis; membrane depolarization during cardiac muscle cell action potential; regulation of resting membrane potential; cellular response to mechanical stimulus; positive regulation of potassium ion transmembrane transport; regulation of cardiac muscle cell contraction
Cellular component: membrane; plasma membrane; voltage-gated potassium channel complex; T-tubule; dendrite; dendritic spine; glutamatergic synapse; intercalated disc; neuronal cell body; postsynaptic membrane
Genetic constraint (gnomAD): Loss-of-function variants: 12 observed, 29.87 expected, observed/expected ratio (o/e) 0.4, 90% interval 0.26 to 0.65. The upper end of that interval is the gene's LOEUF score, 0.65, which puts it in group 2 of 6, group 1 being the genes least tolerant of losing a copy. Missense variants: 320 observed, 579.99 expected, observed/expected ratio (o/e) 0.55, 90% interval 0.5 to 0.61. Synonymous variants: 200 observed, 213.18 expected, observed/expected ratio (o/e) 0.94, 90% interval 0.83 to 1.05.
Gene-disease validity (ClinGen):
ClinGen rates the evidence that KCNJ2 causes each of these diseases.
short QT syndrome (autosomal dominant): Moderate.
long QT syndrome (autosomal dominant): Limited.
catecholaminergic polymorphic ventricular tachycardia (autosomal dominant): Disputed. Catecholaminergic polymorphic ventricular tachycardia (CPVT) is a severe genetic arrhythmogenic disorder characterized by adrenergically induced ventricular tachycardia (VT) manifesting as syncope and sudden death.
congenital heart disease (inheritance undetermined): No Known Disease Relationship. A heart disease that is present at birth.
Homologues: Orthologues: chimpanzee KCNJ2 (100% identical), macaque KCNJ2 (100% identical), guinea pig KCNJ2 (99% identical), pig KCNJ2 (99% identical), dog KCNJ2 (99% identical), rabbit KCNJ2 (99% identical), rat Kcnj2 (99% identical), mouse Kcnj2 (99% identical), tropical clawed frog kcnj2 (90% identical), zebrafish kcnj2a (84% identical), zebrafish kcnj2b (74% identical). Paralogues in human: KCNJ12 (71% identical), KCNJ18 (71% identical), KCNJ4 (62% identical), KCNJ14 (59% identical), KCNJ3 (47% identical), KCNJ6 (46% identical), KCNJ5 (45% identical), KCNJ9 (44% identical), KCNJ16 (41% identical), KCNJ8 (41% identical), KCNJ11 (40% identical), KCNJ1 (37% identical), and 3 more.
Diseases named in the same sentence as KCNJ2 in open-access papers:
KCNJ2 is named in the same sentence as 146 diseases in open-access papers, as found by Europe PMC text mining. Sharing a sentence is not in itself a finding about the gene and the disease. The quoted sentences say what the papers report.
Andersen-Tawil syndrome (73 papers, 2006 to 2025). "Mutations in KCNJ2 are associated with several sudden death syndromes including Andersen-Tawil Syndrome which is loss-of-function (LOF) and Short QT Syndrome which is gain-of-function (GOF)." (PMID 41308991, 2025). "Hundreds of KCNJ2 (Kir2.1) variants of uncertain significance (VUS) have been associated with Andersen-Tawil Syndrome (ATS)." (PMID 41308991, 2025). "The mutation of KCNJ2 was widely reported in Andersen’s Syndrome, characterized by recurrent paralysis, irregular heartbeat, and defects in bone growth." (PMID 37683138, 2023). "Mutations in the Inwardly rectifying potassium channels Kir2.1 encoded by KCNJ2 causing loss of function are associated with a rare clinical phenotype called Andersen-Tawil syndrome (ATS), which contains pleomorphic ventricular tachycardia." (PMID 35783865, 2022). "Genetic screening revealed heterozygous variant c.635G>A (p.Arg218Gln) in the KCNJ2 gene, a known cause of Andersen-Tawil syndrome, and additional rare variant p.Thr983Ile in the KCNH2 gene." (PMID 35456365, 2022). "Their role in arrhythmogenesis is highlighted in Andersen's syndrome caused by an autosomal dominant loss‐of‐function mutation in the KCNJ2 gene encoding the Kir2.1." (PMID 36165125, 2022). "Another reported gene is KCNJ2, and its heterozygous missense mutation (R67W) was detected in Andersen syndrome with cardiovascular malformation of the bicuspid aortic valve." (PMID 36071494, 2022). "Pathogenic variants in KCNJ2 were first associated with Andersen Tawil Syndrome (ATS) in 2001 and until now account for 80% of the cases." (PMID 34899860, 2021). "Mutations that disrupt the inwardly rectifying potassium channel (Kir2.1), encoded by the KCNJ2 gene, cause Andersen-Tawil syndrome." (PMID 32581710, 2020). "Andersen’s syndrome occurs as a result of a mutation in gene KCNJ2 located on chromosome 17 encoding potassium channel Kir2.1." (PMID 33005530, 2020). "Andersen-Tawil syndrome (“LQT7”) is a multisystem disorder due to loss-of-function mutations in KCNJ2, the gene encoding the Kir2.1 protein, which assembles in tetramers to build the channels that carry the inward rectifier K+ current (IK1)." (PMID 30123799, 2018). "Defects in KCNJ2 have beenlinked to Andersen-Tawil Syndrome (ATS) and novel mutations have beendescribed in two families with LQTS without the ATS phenotype." (PMID 29672598, 2018). "Mutations in the KCNJ2 gene have been associated with Andersen-Tawil syndrome (ATS), Short QT syndrome as well as with Catecholaminergic polymorphic ventricular tachycardia (CPVT)." (PMID 29017447, 2017). "A loss-of-function mutation in gene KCNJ2 encoding Kir2.1 causes Andersen-Tawil Syndrome, an autosomal dominant disorder characterized by QT interval prolongation and ventricular arrhythmia." (PMID 29290967, 2017). "Up to now, all KCNJ2 mutations, which were functionally characterized and associated with the Andersen-Tawil syndrome, resulted in complete loss-of-function when expressed as homotetramers." (PMID 29017447, 2017). "Mutations in the KCNJ2 gene encoding the ion channel Kir2.1 have been linked to the Andersen-Tawil syndrome (ATS)." (PMID 29017447, 2017). "– KCNJ2 loss-of-function mutation: cause Andersen-Tawil syndrome a condition characterized by long QT-syndrome, cardiac arrhythmia, skeletal abnormalities, mood disorders and seizures." (PMID 25784856, 2015). "Loss-of-function mutations in the KCNJ2 gene are responsible for the rare Andersen-Tawil syndrome (OMIM 170390) a condition characterized by long QT-syndrome, cardiac arrhythmia, skeletal abnormalities, periodic paralysis, mood disorders, and seizures." (PMID 25784856, 2015). "The role of Kir2.1 in ventricular arrhythmia vulnerability has been highlighted by the recently described Andersen’s syndrome, in the guinea pig heart model of ventricular fibrillation, in a transgenic mouse model and recently in human KCNJ2 mutation." (PMID 26222262, 2015).
Andersen-Tawil syndrome (continued). "Mutations in the KCNJ2 gene, encoding the inwardly rectifying K+ channel Kir2.1, are responsible for the rare Andersen-Tawil syndrome (OMIM 170390), a condition characterized by periodic paralysis, cardiac arrhythmia and skeletal abnormalities." (PMID 24794859, 2014). "Dominant negative mutations in KCNJ2 cause the Andersen syndrome, characterized by ventricular arrhythmias, periodic paralysis, and a number of skeletal and cardiac abnormalities." (PMID 23284291, 2012). "KCNJ2 has been implicated in Pierre Robin sequence and Andersen-Tawil syndrome, which show abnormalities in tooth development (missing teeth, delays in eruption) and are characterized by craniofacial anomalies such as narrowing of the jaw and cleft palate." (PMID 20195514, 2010). "Mutations in KCNJ2 will result in an inability to repolarize the skeletal muscle cell, resulting in a similar clinical manifestation and the additional association of cardiac arrhythmias resulting in Andersen-Tawil syndrome." (PMID 41191903, 2025). "SNPs are distributed in the human genome in a non-random fashion, and double mutations are considered secondary events in the context of an already existing SAP, as is exemplified with the Andersen-Tawil syndrome, where two missense mutations in the KCNJ2 gene are located on the same allele." (PMID 36671572, 2023). "Andersen-Tawil syndrome (ATS) is a rare periodic paralysis caused by the KCNJ2 gene mutation." (PMID 37456645, 2023). "Dominant-negative mutations in the KCNJ2 gene, encoding the K+ channel Kir2.1, also cause primary HypoPP in Andersen-Tawil syndrome, a disorder clinically distinct from HypoPP1 and 2 since the neuromuscular phenotype is associated with cardiac arrhythmia and bone deformities." (PMID 34671263, 2021). "The importance of Kir2.1 in contributing to native IK1 is demonstrated by the fact that loss-of-function KCNJ2 mutations have been implicated in Andersen-Tawil syndrome, which causes one form of long QT syndrome (long QT type 7) as well as extra-cardiac abnormalities." (PMID 35115940, 2021). "Two genes, CACNA1C and KCNJ2, were reported to be associated with multiple organ system involvement (Timothy Syndrome and Andersen-Tawil Syndrome, respectively), which include a prolonged QT interval and ventricular arrhythmias as part of the phenotypic expression." (PMID 31983240, 2020). "In addition, mutations in KCNJ2 that result in reduced function of the inwardly rectifying potassium channel Kir2.1 are associated with PP in Andersen-Tawil syndrome." (PMID 31772215, 2019). "Mutations in KCNJ2 leading to loss-of-function of Kir2.1 have been linked with Andersen-Tawil syndrome, a cardiovascular disease characterized by QT prolongation, predisposition to cardiac tachyarrhythmias as well as skeletal abnormalities, mood disorders and seizures." (PMID 29615871, 2018). "Mutations in the KCNJ2 gene have been reported to cause Andersen-Tawil syndrome." (PMID 29017447, 2017). "Mutations in the potassium channel KCNJ2 gene (inward-rectifier potassium ion channel) often presents clinically as Andersen-Tawil syndrome; however, penetrance is extremely variable, with some carriers of the mutation displaying little or no phenotypic expression." (PMID 27682153, 2016). "Mutations in KCNJ2, which encodes the a-subunit of Kir 2.1, an inwardly-rectifying potassium channel, have been identified as the genetic defects underlying the clinical phenotype of Andersen-Tawil syndrome." (PMID 16943893, 2006). "Noting that to date, about 60% of Andersen syndrome patients are found to have mutations in Kir2.1, screening for KCNJ2 mutations also provides an increasingly valuable tool in either confirming or establishing diagnosis in a phenotypically heterogenous condition." (PMID 16943893, 2006). "Andersen-Tawil Syndrome (ATS) is a rare disease defined by the association of cardiac arrhythmias, periodic paralysis and dysmorphic features, and is caused by KCNJ2 loss-of-function mutations." (PMID 34899860, 2021).
Andersen-Tawil syndrome (continued). "KCNJ2 mutations cause a cardiodysrhythmic type of periodic paralysis known as Andersen-Tawil syndrome (ATS; MIM 170390)." (PMID 27299157, 2016). "Furthermore, mutations in the KCNJ2 gene (encoding inward-rectifier potassium channel Kir2.1), which have been linked to Andersen-Tawil syndrome (ATS), could also result in a PP phenotype, although typically accompanied by ventricular arrhythmias and dysmorphism." (PMID 36779057, 2023). "Andersen-Tawil syndrome (ATS), also called LQTS7, is an autosomal dominant potassium channelopathy characterized by gene mutations of KCNJ2 (or ATS1)." (PMID 32575374, 2020). "Andersen-Tawil syndrome (KCNJ2) and Timothy syndrome (CACNA1C) are rare conditions affecting multiple systems whose phenotypic expression includes QT prolongation and ventricular arrhythmias." (PMID 31983240, 2020). "KCNJ2 expression mainly in cardiac muscle cells suggests a role for this protein in the development of Andersen syndrome and atrial fibrillation." (PMID 32184906, 2020). "TRPM4 enlarges the subgroup of LQT genes (KCNJ2 in Andersen syndrome and CACNA1C in Timothy syndrome) known to increase the QT interval through a more complex pleiotropic effect than merely action potential alteration." (PMID 28315637, 2017). "Genes in this region associated with human phenotypes include PRKAR1A (Carney complex) and KCNJ2 (Andersen/Andersen-Tawil syndrome)." (PMID 24892279, 2014). "In LQT7, which is also known as the Andersen-Tawil syndrome, mutations in the KCNJ2 gene result in disturbed Kir2.1 channels, which are expressed in multiple organs." (PMID 23304551, 2012). "KCNJ2 (LQT7- Andersen syndrome): In 2001, this disease was successfully mapped to the locus 17q in a large family." (PMID 18478063, 2008). "Andersen-Tawil syndrome is a rare LQTS associated with physical abnormalities and hypokalemic periodic paralysis and is primarily caused by loss of function mutations in KCNJ2 (Kir2.1), resulting in reduced IK1 current." (PMID 37775650, 2023). "Clinically, KCNJ2 is involved in the development of Andersen syndrome and atrial fibrillation." (PMID 32184906, 2020). "Genetic testing for muscular dystrophies (EMD, LMNA, CAV3) and for Andersen-Tawil syndrome (KCNJ2) was negative, as were mitochondrial DNA mutation studies." (PMID 25184293, 2014). "The level of evidence for the gene KCNJ2 was only limited for the cardio-specific phenotype of LQTS, whereas both genes (CACNA1C and KCNJ2) were classified to have definitive evidence for causing multiorgan syndromes (respectively: Timothy syndrome and Andersen-Tawil syndrome)." (PMID 34031550, 2021). "Five families with PPP included: hypokalemic periodic paralysis type 1 (HypoPP1, CACNA1S, 1/5), hypokalemic periodic paralysis type 2 (HypoPP2, SCN4A, 2/5), normokalemic periodic paralysis (NormoPP, SCN4A, 1/5), and Andersen-Tawil syndrome (ATS, KCNJ2, 1/5)." (PMID 33345742, 2021). "Although we could not find any deleterious KCNJ2 mutations in our TPP cases through direct sequencing, earlier studies showed that Kir2.1 mutations lead to Andersen-Tawil syndrome (ATS) manifesting as periodic paralysis, ventricular ectopy, and dysmorphic features." (PMID 25885757, 2015).